CXCR4 (C-X-C motif chemokine receptor 4)
Diseases named in the same sentence as CXCR4 in open-access papers (continued):
Sharing a sentence is not in itself a finding about the gene and the disease.
renal fibrosis (continued). "We also testified the effects of ICG‐001, the inhibitor of β‐catenin signalling, on CXCR4‐aggravated renal fibrosis." (PMID 32119183, 2020). "Here, we adopted different CKD mouse models and cultured human proximal tubular cell line (HKC‐8) to examine the expression of C‐X‐C motif chemokine receptor 4 (CXCR4) and β‐catenin signalling, as well as their relationship in renal fibrosis." (PMID 32119183, 2020). "Recently we have showed that CXCR4 antagonism significantly attenuated the induction of cardiac fibrosis, renal fibrosis and left ventricular hypertrophy in the DOCA model of mineralocorticoid excess." (PMID 26214690, 2015). "Collectively, these observations indicate that local SDF-1/CXCR4 signaling functions to preserve microvascular integrity and prevent renal fibrosis." (PMID 24637920, 2014). "Collectively, these observations highlight a hitherto unrecognized role for local SDF-1/CXCR4 signaling in preserving microvascular integrity and preventing coincident renal fibrosis in CKD." (PMID 24637920, 2014). "Ectopic CXCR4 further aggravated the activation of β‐catenin and induced renal fibrosis." (PMID 38213100, 2024). "Additionally, in the context of chronic kidney disease, the CXCR4 inhibitor Plerixafor shows promise as a targeted therapy for renal fibrosis by inhibiting the STAT3 pathway." (PMID 38920657, 2024). "The targeted inhibition of CXCR4, whether by its antagonists or delivered gene therapy, would be a new and effective therapeutic strategy for preventing renal fibrosis." (PMID 38213100, 2024). "Targeted inhibition on the CXCR4/β‐catenin pathway could maintain fatty acid metabolism and retard renal fibrosis." (PMID 38213100, 2024). "Hence, our findings reveal a new mechanism of renal fibrosis and suggest that targeted inhibition of CXCR4 provides a new therapeutic strategy for treating CKD." (PMID 38213100, 2024). "Since the i-body alone has a short half-life in blood and lower affinity, we sought to test if the second-generation Fc-fused anti-CXCR4 i-body AD-214 could mitigate renal fibrosis when given at a lower dosage and a longer dosing interval than AD-114." (PMID 39684834, 2024). "Recent studies have uncovered that tubular STAT6, a downstream gene of CXCR4, could promote lipid accumulation and renal fibrosis by suppressing FAO in the UUO model through a sis‐inducible element situated in the promoter region of the protein." (PMID 38213100, 2024). "This upregulation of CXCR4 at an early stage may lay the foundation for a preventative effect of AD-114 on subsequent renal fibrosis." (PMID 35015734, 2022). "In experimental transplant models, a CXCR4 antagonist burixafor significantly attenuated the incidence rate of acute rejection after heart transplantation in minipigs and CXCR4 antagonism inhibited the expression of profibrotic genes and attenuated renal fibrosis in rats." (PMID 33776571, 2021). "Ectopic expression of CXCR4 evidently aggravated renal fibrosis in UUO mice." (PMID 32119183, 2020). "Our studies also suggest that targeted inhibition of CXCR4 may provide better therapeutic effects on renal fibrosis by inhibiting multiple downstream signalling cascades." (PMID 32119183, 2020). "Examination of kidney sections by light microscopy revealed that SNx surgery was associated with an expected increase in glomerulosclerosis and tubulointerstitial collagen IV deposition, with both of these indicators of renal fibrosis being augmented with CXCR4 antagonism in SNx rats." (PMID 24637920, 2014). "Accordingly, in the present study we sought to combine studies conducted in experimental animals, cultured cells and human biopsy tissue to define the role of SDF-1/CXCR4 signaling in CKD, focusing on the bidirectional relationship between renal fibrosis and microvascular loss." (PMID 24637920, 2014).
renal fibrosis (continued). "Additionally, in a CKD rat model, therapy with peripheral blood-derived endothelial progenitor cells elevated SDF-1α expression at the protein level, suggesting a role for local SDF-1/CXCR4 signaling in preserving microvascular integrity and preventing renal fibrosis." (PMID 37711613, 2023). "Interestingly, administration of ICG‐001 could significantly block CXCR4‐induced renal fibrosis, further suggesting the mediating role of β‐catenin in CXCR4 cascade." (PMID 32119183, 2020). "Also, CXCR4 antagonists ameliorate renal fibrosis in the UUO kidney." (PMID 30818366, 2019). "They postulated that local SDF-1/CXCR4 could function to prevent renal fibrosis." (PMID 25029540, 2014). "To further confirm the role of β‐catenin in CXCR4‐induced renal fibrosis, we pretreated HK‐2 cells with ICG‐001, a small molecule inhibiting β‐catenin‐mediated gene transcription, and then transfected cells with pFlag‐CXCR4 plasmid." (PMID 38213100, 2024). "AMD3100, a CXCR4 receptor blocker, and gene knockdown of CXCR4 significantly inhibited the activation of JAK/STAT and β‐catenin signalling, protected against tubular injury and renal fibrosis." (PMID 32119183, 2020). "To identify the role of CXCR4 in renal fibrosis, we first examined the expression of CXCR4 and CXCL12 (SDF‐1α), the ligand of CXCR4, in various CKD models." (PMID 32119183, 2020). "Collectively, these results suggest a renoprotective role of AD-114 as it inhibited the chemotactic function of CXCR4 as well as blocked CXCR4 downstream p38 MAPK and PI3K/AKT/mTOR signaling, which establish a therapeutic strategy for AD-114 targeting CXCR4 to limit renal fibrosis." (PMID 35015734, 2022). "To elucidate the role of SDF-1/CXCR4 signaling in CKD we first determined gene expression of both receptor and ligand in the kidneys of rats that had undergone subtotal nephrectomy (SNx), a well-established model of progressive renal fibrosis." (PMID 24637920, 2014). "However, the relationship between CXCR4 and cell senescence in renal fibrosis has not been demonstrated." (PMID 38213100, 2024). "Previous reports have shown that chronically high CXCR4 expression in multiple effector cell types can contribute to the pathogenesis of renal fibrosis by altering their biological profile, and crosstalk between CXCR4 and TGF-β1 pathways contributes to the progression of renal fibrosis." (PMID 35015734, 2022). "BM-mobilized macrophages and fibrotic cells express CXCR4 and infiltrated CXCL12-enriched tissue; however, we did not identify the type of cell that contributes to renal fibrosis in UUO kidney." (PMID 30818366, 2019).
heart failure (20 papers, 2015 to 2025). Inability of the heart to pump blood at an adequate rate to meet tissue metabolic requirements. "Cardiomyocyte CXCR4 expression has previously been implicated in preventing adverse ventricular remodelling and in the development of heart failure after ischaemia-reperfusion injury." (PMID 30738798, 2019). "Herein, we aimed to determine the role of macrophagic CXCR4 in heart failure with preserved ejection fraction (HFpEF)." (PMID 35173552, 2022). "In vivo transplantation into acutely and chronically injured porcine hearts illustrated CXCR4-dependent homing, de novo formation of heart muscle, scar-volume reduction and prevention of heart failure progression." (PMID 35550611, 2022). "There is mounting evidence suggesting that antagonism of CXCR4 attenuates cardiac fibrosis and improves myocardial function in various heart failure models." (PMID 34072818, 2021). "CXCR4 knockout in cardiomyocytes leads to progressive cardiac dysfunction and later to cardiac failure." (PMID 34884827, 2021). "It has been demonstrated that patients with cardiac failure have increased levels of CXCR4 expression and its ligand CXCL12/SDF1." (PMID 33924458, 2021). "Further studies are warranted to examine the potential utility of manipulation of the SDF-1/CXCR4 axis as a clinical therapeutic strategy in heart failure." (PMID 30837882, 2019). "This notion is based upon our finding, and by others, that levels stromal derived factor-1 (SDF-1), which binds to CXCR4, are elevated in experimental and human heart failure." (PMID 30837882, 2019). "Our present data indicate that CXCR4 cKO mice developed a progressive heart failure and die by 13 months of age." (PMID 31071921, 2019). "Cardiomyocyte specific-CXCR4 knockout (CXCR4 cKO) mice demonstrate a progressive cardiac dysfunction leading to cardiac failure by 12-months of age." (PMID 31071921, 2019). "We anticipated that, based on our present and previously published data, CXCR4 cKO animals would develop cardiac dysfunction and progress to clinical heart failure because of improper calcium handling secondary to inappropriate β-adrenergic activation." (PMID 31071921, 2019). "Using a combination of MRI, hemodynamic, and histological analysis, we showed that CXCR4 cKO mice develop a progressive heart failure phenotype that leads to premature death." (PMID 31071921, 2019). "Clinical investigation has revealed up-regulation of both SDF-1α and CXCR4 in cardiac tissue from patients with end-stage heart failure 8, implying the important role of this signal axis in the development of human heart failure." (PMID 25824297, 2015). "Thus, the CXCR4 pathway is not only closely linked to the pathogenesis of several CVDs, but due to its role in the pro-inflammatory signaling response, it may be a promising therapeutic target for conditions such as heart failure, hypertension, and pregnancy-associated complications." (PMID 40859641, 2025). "Furthermore, more recent studies indicate that CXCR4 is also involved in the diastolic cardiac dysfunction observed in heart failure with preserved ejection fraction." (PMID 40859641, 2025). "CXCR4 plays a crucial role in promoting inflammatory responses and tissue remodeling, while IL-1 and IL-6 are pro-inflammatory cytokines involved in the progression of myocardial injury and heart failure." (PMID 40427493, 2025). "In a mouse model of heart failure with preserved ejection fraction, increased CXCR4-positive macrophages were found in the circulation and the myocardium, which was associated with myofibroblast differentiation, fibrosis and an increased in inflammatory cytokines." (PMID 36928240, 2023). "It was found that CXCL12_CXCR4 was highly expressed in each stage of cardiac hypertrophy, indicating that endothelial cells played a crucial role in myocardial remodeling by secreting some chemokines and cytokines and regulating immune cell chemotaxis in heart failure." (PMID 36805782, 2023).
heart failure (continued). "Increases were observed in PET signals for CXCR4, a marker of old activated neutrophils that cause tissue damage, and for CCR2 which marks a pro-inflammatory subset of monocytes-macrophages, that associates with adverse left ventricle remodeling and heart failure progression." (PMID 36061565, 2022). "In addition, CXCR4 gene transfer can prevent pressure overload induced heart failure in murine model 11, implying that myocardial CXCR4 up-regulation may serve as a protective molecular mechanism in response to various myocardial stress conditions." (PMID 25824297, 2015). "Since β-ARs play a central role in heart failure pathogenesis via their modulation of calcium channel activity, a detailed analysis of the CXCL12/CXCR4 and/or CXCL12/CXCR7 relationship is warranted." (PMID 31071921, 2019). "The modules related to germ cell migration and disrupted cellular calcium ion homeostasis were solely detected in heart failure arising from ISCM, with increased CXCR4, CCL5, and CXCL12." (PMID 29160422, 2017). "We found a significant upregulation of cardiac tissue CXCR4 mRNA, which has been shown to prevent adaptive ventricular remodelling after pressure overload and increased ACTA1 levels, that has been shown to be a marker for heart failure." (PMID 33802976, 2021). "Our results demonstrated that CXCR4 plays a non-developmental role in regulating cardiac function and that CXCR4 cKO mice develop a progressive cardiomyopathy leading to clinical heart failure." (PMID 31071921, 2019). "Moreover; cardiac specific CXCR4 knockout mice show significant hypertrophy and develop cardiac dysfunction in response to chronic catecholamine exposure in an isoproterenol-induced (ISO) heart failure model." (PMID 31071921, 2019).
multiple sclerosis (20 papers, 2016 to 2026). A progressive autoimmune disorder affecting the central nervous system resulting in demyelination. "In active multiple sclerosis, CXCR4 + leukocytes are trafficked to the brain lesions to cause tissue damage by CXCL12 secreted by endothelial cells." (PMID 38684986, 2024). "These synthetic receptor antagonists inhibited EAE by interfering with the action of CXCR3 and CXCR4 in a mouse model of multiple sclerosis called experimental autoimmune encephalomyelitis (EAE)." (PMID 39070795, 2024). "CXCR4 has been shown to contribute to the pathogenesis of Lewy body dementia and multiple sclerosis by promoting TC recruitment and Th17/Treg imbalance." (PMID 36301664, 2022). "Imbalances in the CXCL12/CXCR4/ACKR3 axis are associated with diseases, including cancer, multiple sclerosis, and RA." (PMID 34489952, 2021). "T helper cells expressing granulocyte‐macrophage colony‐stimulating factor and the CXCR4 expanded in patients with multiple sclerosis." (PMID 33135337, 2020). "An altered pattern of CXCL12 expression in brain has been reported in multiple sclerosis, suggesting the involvement of the CXCR4/CXCL12 axis in the leukocyte infiltration that characterizes this pathology." (PMID 27766097, 2016). "Similarly, CXCR4+ NK cells were observed specifically during the remission phase in multiple sclerosis." (PMID 36631780, 2023). "Coexpression of Plac8 and Cxcr4 is found in circulating monocytes and monocyte-derived antigen-presenting cells in an experimental model of multiple sclerosis, suggesting chronic inflammation may be required for the miR-181/Plac8/Cxcr4 axis to be activated." (PMID 36821386, 2023). "Thus in multiple sclerosis, CXCR4 restricts T cells migrating across astrocyte endfeet and entering the brain." (PMID 35464424, 2022). "In addition, SDF-1/CXCR4 signaling has been reported to contribute to chemotaxis and differentiation into oligodendrocytes of engrafted neural stem cells resulting in axonal remyelination in a mouse model of multiple sclerosis." (PMID 30622535, 2018). "CXCR4 and PTGER4 were higher expressed in subcortical white matter compared to cortical grey matter microglia, and ADGRG1 was downregulated in microglia obtained from normal-appearing white and grey matter tissue of multiple sclerosis (MS) brains." (PMID 34054860, 2021).
cholangiocarcinoma (19 papers, 2013 to 2026). A carcinoma that arises from the intrahepatic biliary tree (intrahepatic cholangiocarcinoma) or from the junction, or adjacent to the junction, of the right and left hepatic ducts (hilar cholangiocarcinoma). "With respect to the CXCR4-CXCL12 axis, with high CXCR4 expression in human cholangiocarcinoma tissues, was implicated in cholangiocarcinoma development and progression." (PMID 38702814, 2024). "HULC has been reported to promote cell migration and invasion in cholangiocarcinoma through a ceRNA manner regulating CXCR4." (PMID 30305026, 2018). "CXCL12/CXCR4 signaling promotes cholangiocarcinoma progression and metastasis via the canonical Wnt pathway, and Wnt5a is a critical mediator of human and murine T cell CXCL12/CXCR4 signaling and migration." (PMID 28380463, 2017). "We also found that HULC was targeted by miR-372 and miR-373 and further activated the chemokine receptor CXCR4 in the progression of migration and invasion in cholangiocarcinoma cells." (PMID 27809873, 2016). "Human HSCs in culture release stromal derived factor-1 (SDF-1), and co-cultured cholangiocarcinoma (CCA) cells are induced by SDF-1 binding to CXCR4 followed by increased migration of CCA cells." (PMID 24978432, 2014). "When treated by AMD3100, the motility and invasiveness of CD24 (+) cells were decreased, implying the importance of CXCR4 in cholangiocarcinoma cell invasion." (PMID 25471741, 2014). "We previously demonstrated that the chemokine receptor CXCR4 had a major role in the invasiveness of cholangiocarcinoma cells." (PMID 24179538, 2013). "The present study indicates that CXCR4 and ERK1/2 are induced by CD24 and that these proteins are associated with cholangiocarcinoma cell invasion." (PMID 24179538, 2013). "Additionally, treatment with bortezomib in combination with CXCR4 inhibitor, a checkpoint inhibitor, has been shown to decrease cholangiocarcinoma tumor mass and volume in mice within 60 days." (PMID 38339421, 2024). "Additionally, a cell‐type‐dependent correlation of CD24 to the chemokine receptor CD184 (CXCR4) was found; for example, in pre‐B lymphocytes, CD24 negatively regulated CD184, while in cholangiocarcinomas, CD24 induced CD184 expression." (PMID 34293822, 2022). "For instance, the expression of HULC and H19 is triggered by oxidative stress to upregulate Interleukin-6 (IL-6) and the C-X-C chemokine receptor type 4 (CXCR4) sequestering Let-7a/b and miR-372/-373, respectively, to promote cholangiocarcinoma migration and invasion." (PMID 32492865, 2020). "The present study demonstrated that blocking CXCR4 signaling with AMD3100 results in decreased motility and invasion ability in CD24+ and CD24− cells (although to a greater extent in CD24+ cells), indicating that CXCR4 is important in cholangiocarcinoma cell invasiveness." (PMID 24179538, 2013). "Taken together, SCLC, cholangiocarcinoma, highly dedifferentiated NEN, and ACC may be the most promising tumor entities for a CXCR4-directed PET." (PMID 35674738, 2022).